MSLN (mesothelin)
Diseases named in the same sentence as MSLN in open-access papers (continued):
Sharing a sentence is not in itself a finding about the gene and the disease.
cancer (continued). "The differential expression of mesothelin in normal and cancer tissues makes it a promising candidate for targeted therapeutics." (PMID 30134520, 2018). "Our studies provide new clues to the pro-apoptotic mechanism of panbinostat, and provide strong evidence that the combination of LMB-100 and panbinostat should be considered for the treatment of cancers expressing mesothelin." (PMID 29152082, 2017). "Due to the weak expression in normal tissues and strong expression in several cancers, mesothelin is considered as an attractive target for immune-based therapies." (PMID 28356156, 2017). "The limited expression in normal tissues and high expression in many cancers renders MSLN a potential CAR T cell target." (PMID 29312333, 2017). "CA-125 binds to mesothelin and this interaction has been suggested to play a role for the ability of cancer cells to metastasize e.g. to the peritoneum." (PMID 29273809, 2017). "Because of its prevalence in cancers, MSLN has recently been targeted for immunotherapy, while the soluble MSLN fragment has been investigated as a biomarker for cancer diagnosis." (PMID 28288645, 2017). "An in vitro evaluation revealed that MSLN increased cancerous cell proliferation significantly, and silencing the MSLN gene decreased cancer cell proliferation, migration and invasiveness." (PMID 29059207, 2017). "ShRNA knockdown and overexpression of MSLN were performed in human cancer cell lines and corresponding normal cells, respectively." (PMID 28288645, 2017). "Since humoral immune responses are clinically significant in cancer, we quantified theamount of mesothelin-specific antibodies in serum obtained from patients with GBM as well in serum from healthy individuals." (PMID 29113296, 2017). "LMB-100 (RG7787) is a recombinant immunotoxin, which kills mesothelin-expressing cancer cells and now being evaluated in phase 1 trials." (PMID 29152082, 2017). "Our results showed that hYP218 bound to mesothelin specifically and was internalized homogenously within 6 hours of incubation in mesothelin expressing cancer cells." (PMID 26981775, 2016). "All of these cancers express mesothelin, the target of the SS1 targeting moiety found in the tested immunotoxins." (PMID 27463727, 2016). "The identification of a sufficiently immunogenic antigen has been a major obstacle for the development of a clinically-effective cancer vaccine, though several potential vaccines (such as Muc1 and mesothelin) have reached human trials." (PMID 27343548, 2016). "Investigation of the promoter of another MPM marker, mesothelin, has led to the discovery of a cancer-specific element driving mesothelin overexpression in cancers." (PMID 26848772, 2016). "We identified the high affinity of the mesothelin/MUC16 interaction as the dominant parameter for the rapid attachment of targeted TR3 fusion proteins to MUC16-positive cancer cells with the TR3/DR interaction playing a secondary role." (PMID 27120790, 2016). "In our current study, we have characterized a newly designed variant of the TNF superfamily member TRAIL, designated TR3, targeted to the cancer biomarker mesothelin, using a single chain antibody format (SS-TR3)." (PMID 26935795, 2016). "Incorporation of a spacer-into the mesothelin surface antigen or the cancer drug itself-converted SS-TR3 into a cis-acting phenotype." (PMID 26935795, 2016). "This suggests that different transcription factors act on the mesothelin promoter in normal cells and cancer cells." (PMID 26848772, 2016). "In this study we explored the potential therapeutic applications of an adenovirus with PK-based tropism against cancers expressing mesothelin." (PMID 25933160, 2015). "Notwithstanding the limitations, our results show that a radiolabelled anti-mesothelin monoclonal antibody localizes to the primary and metastatic sites of mesothelin-expressing cancers." (PMID 25756664, 2015).
cancer (continued). "With these properties of MSLN expression, MSLN can be a promising targeting molecule for a diverse range of cancers." (PMID 25883990, 2015). "The cancer cell lines were combined with recombinant live-attenuated, double-deleted Listeria monocytogenes, engineered to secrete MSLN into the cytosol of infected antigen presentation cells." (PMID 26172299, 2015). "Because of its limited distribution in normal tissues and elevated expression in cancers, MSLN has the potential to become a suitable target for a wide range of cancer diagnosis and therapy by using its specific antibodies." (PMID 25883990, 2015). "MSLN is also known to be overexpressed to a lesser extent in multiple other human cancers such as endometrial, lung, stomach, triple negative breast, cervical, non-small cell lung cancer (NSCLC) and head and neck cancers (HNSCC)." (PMID 26172299, 2015). "This is the first study to show localization of an anti-mesothelin antibody in tumors of patients with mesothelin-expressing cancers." (PMID 25756664, 2015). "Mesothelin is essential to invasion and metastasis of cancer cells and the side effects of destroying normal mesothelin producing cells is minimal." (PMID 25933160, 2015). "Overall, the new antibodies described here should be useful for emerging mesothelin-targeted cancer therapies and diagnostics." (PMID 25996440, 2015). "The membrane-bound form of MSLN is present on a wide range of cancer cells and its expression in normal tissues is relatively limited in the mesothelial cells." (PMID 25883990, 2015). "To evaluate their potential in cancer diagnosis, we found that the antibodies were suitable for immunohistochemistry and they were highly sensitive for the detection of soluble mesothelin in ELISA." (PMID 25996440, 2015). "Amatuximab is a chimeric high-affinity monoclonal IgG1/k antibody targeting mesothelin that is being developed for treatment of mesothelin-expressing cancers." (PMID 25756664, 2015). "Amatuximab (MORAb-009) is a chimeric high-affinity monoclonal IgG1/k antibody targeting mesothelin which is being developed for the treatment of mesothelin-expressing cancers." (PMID 25756664, 2015). "Part of the reason is supposed to be that the human carcinoma cells were “invading” in mouse tissue and overexpressed MSLN." (PMID 25883990, 2015). "The results demonstrate that the frequency of circulating anti-MSLN specific CD4+ T cells in cancer patients were significantly higher than that observed in the benign pancreatic disease patients (p = 0.0053) and normal controls (p = 0.0004)." (PMID 24520352, 2014). "For mesothelin a role in cell adherence, proliferation, and cancer progression has been implied but less is known about miR-103a-3p." (PMID 25469901, 2014). "Our results confirmed their data and demonstrated that soluble MSLN levels are increased in the plasma of cancer patients and benign pancreatic disease patients compare to that in healthy donors." (PMID 24520352, 2014). "It was found that MSLN is present at low levels in a restricted set of normal adult tissues, including the mesothelium, but it is overexpressed aberrantly by several cancers, such as MPM, and pancreatic (PC) and ovarian carcinomas (OC)." (PMID 24465798, 2014). "(c) Mesothelin-specific CD4+ T cell response is directly inhibited by elevated IL-10 in cancer patients." (PMID 24520352, 2014). "This new cancer immunotherapy has the potential to be cost-effective and broadly applicable to tumors that overexpress mesothelin." (PMID 24565018, 2014). "This mesothelin/MUC16 ligand/receptor interaction serves to anchor soluble TRAIL to the surface of MUC16-positive cancer cells, thus converting the soluble drug into a membrane bound form of TR3." (PMID 24447304, 2014). "Anti-MSLN CD8+ T cell responses were detected in 36% of cancer patients (9 out of 25), 20% of benign pancreatic disease patients (3 out of 15) and in only 6.3% of healthy controls (1 out of 16)." (PMID 24520352, 2014).
cancer (continued). "In our current study, we sought to deliver TR3 selectively to the cancer cells employing a native, high-affinity ligand/receptor interaction between mesothelin and MUC16, also known as CA125." (PMID 24447304, 2014). "The relevance of the mesothelin/MUC16 interaction for attaching Meso-TR3 to the cancer cells was verified by competitive blocking experiments using soluble mesothelin." (PMID 24447304, 2014). "In summary, our findings confirm that MSLN should be considered a key molecular target for novel gene-based targeted therapies of cancer." (PMID 24465798, 2014). "The percentage of cancer patients with anti-MSLN T cell response (responders) was significantly higher than that in healthy donors (p = 0.014, χ2 test)." (PMID 24520352, 2014). "In general, the results imply that T cell responses in cancer patients are directed toward a broad repertoire of epitopes within MSLN protein." (PMID 24520352, 2014). "Despite the limited knowledge on the biological role of MSLN in normal and cancer cells, MSLN should also be considered a key molecular target for novel gene-based targeted therapies of cancer." (PMID 24465798, 2014). "To convert TR3 (center) into a MUC16-targeted cancer drug, we inserted the entire cDNA of soluble mesothelin (including the N-terminal FLAG tag) to the 5′-terminus of a TR3 expression plasmid (Meso-TR3)." (PMID 24447304, 2014). "Immunohistochemical studies showed higher expression of ERC/mesothelin in carcinoma lesions compared to surrounding normal tissue, as has been reported previously." (PMID 25347530, 2014). "In this study, we found that IL12-SS1 (Fv) specifically bound mesothelin in several cancer cell lines." (PMID 24260587, 2013). "We, however, were interested in evaluating the effects of direct targeting of Mesothelin on the viability of cancer cells as the first step towards developing a novel therapeutic strategy." (PMID 22485139, 2012). "In support of this concept, the NCI has identified MUC1 and MSLN among the most promising targets for cancer vaccine development, with the former protein listed in the top three." (PMID 22792233, 2012). "Although strategies such as using monoclonal antibodies targeted against MSLN have been tried before, the effect of direct inhibition of MSLN on the viability of cancer cells remains to be investigated." (PMID 22485139, 2012). "We have also investigated the outcome of silencing MSLN on cell signaling characteristics of cancer cells and cell cycle progression in order to further understand the pathways involved in the biological role of this antigen." (PMID 22485139, 2012). "We provide here the first evidence that the soluble cancer biomarker mesothelin binds to macrophages." (PMID 22163010, 2011). "Mesothelin is a GPI-anchored cancer biomarker over-expressed by lung cancers, mesotheliomas, pancreatic and ovarian adenocarcinomas." (PMID 22163010, 2011). "Mesothelin is a cell surface protein present on normal mesothelial cells lining the body cavities and it is highly expressed in several cancers, including ovarian cancers." (PMID 19384429, 2007). "Analysis of mesothelin simulation complexes indicated that the 8CX3‐L151P and 8CX3‐Y144N mutant proteins, when binding at the N‐terminus of cell surface mesothelin, might contribute more to cancer development than the 8CX3‐WT complex." (PMID 40478193, 2025). "The expression of MSLN on the cancer cell surfaces was assessed by flow cytometer." (PMID 40366419, 2025). "Thus, MSLN plays a critical role in cancer progression and its interaction with CA-125 worsens the condition." (PMID 40227616, 2025). "Together, these insights provide a framework for understanding how MSLN may influence not only cancer progression but also the emergence of therapeutic resistance in MSLN-expressing tumors." (PMID 41335396, 2025). "Targeted therapies against MSLN for cancer treatment have recently elicited growing interest." (PMID 41477550, 2025).
cancer (continued). "Notably, MSLN was more uniformly expressed in patient-derived organoids than in respective native cancer tissue." (PMID 40402266, 2025). "Mesothelin protects cancer cells from TNF-α-induced apoptosis by rapidly stimulating Akt phosphorylation under PI3K activation, inhibiting the expression of pro-apoptotic factors, such as Bad and Bax, and promoting the expression of anti-apoptotic genes, such as Bcl-2 and Mcl-1." (PMID 40227645, 2025). "Although the mediators involved in MSLN signal transduction may vary in a cancer-specific manner, they appear to converge on a common downstream target: the MMP7 gene." (PMID 41335396, 2025). "Indeed, a first-in-class topoisomerase I inhibitor ADC (PF-08052666, also known as SGN-MesoC2 or HBM9033) was developed to exert antitumor activity against MSLN-positive cancers." (PMID 41335396, 2025). "Although these findings suggest an inverse correlation between MSLN expression and cellular senescence, the specific role of MSLN in regulating senescence in cancer remains unclear." (PMID 40563707, 2025). "Thus, MSLN has been considered a promising target for the development of targeted therapies against various cancers, notably pleural mesothelioma (PM), an aggressive cancer of the pleura that usually develops after asbestos exposure." (PMID 41477550, 2025). "Notably, various preclinical studies have investigated the application of CAR-T cell therapy in other cancers, including silent solid tumors, such as employing mesothelin-targeting CAR-T cells for the treatment of triple-negative breast cancer." (PMID 39851334, 2025). "Additionally, a specific sequence known as CanScript has been reported to strongly enhance MSLN expression in several malignancies by interacting with a range of cancer-specific transcription factors." (PMID 41335396, 2025). "Given its role in cancer progression, mesothelin has become a key target for CAR-T cell therapy." (PMID 40281554, 2025). "Mesothelin (MSLN) is a protein ubiquitously expressed various cancer types." (PMID 41155765, 2025). "However, the therapeutic potential of meso-CAR-T cells in PCa remains underexplored, partly due to limited knowledge on mesothelin expression in this cancer type, highlighting the need for further investigation." (PMID 40427042, 2025). "Mesothelin is a glycoprotein abundantly expressed in lung, ovarian, colon, pancreatic and mesothelioma cancer and due to its distinctive expression pattern and key role in enhancing cancer dissemination, aggressiveness and drug insensitivity, MSLN is an intriguing marker for cancer therapy." (PMID 40227616, 2025). "Moreover, trace amounts of mesothelin can be detected in the bloodstream of patients with mesothelin-positive cancers, making it a valuable tool for diagnosis and monitoring." (PMID 38799440, 2024). "Given the documented induction of antioxidant gene expression by oncogenes to counteract oxidative stress in cancer cells, we posited that mesothelin may influence antioxidant enzyme expression in AML cells." (PMID 38396817, 2024). "However, potential roles in cell adhesion have been noted and various potential roles in tumorigenesis and progression in mesothelin-expressing cancers have been revealed." (PMID 39315086, 2024). "High IFN-γ produced from T cells derived from MSLN/NCL peptides pulsing PBMCs and effective killing of these MSLN/NCL-specific T cells against MSLN/NCL-positive cancer cells imply that the overexpression of MSLN and NCL could induce MSLC/NCL-specific T cells." (PMID 39294656, 2024). "Region I is also the binding site of many immunotherapy drugs targeting MSLN for cancers." (PMID 39023820, 2024). "Canine mesothelin may play a role similar to human mesothelin in cancer biology because these structurally and functionally important regions of human mesothelin are conserved in canine mesothelin." (PMID 39315086, 2024).
cancer (continued). "However, recent studies have shown that mesothelin is also expressed in a small subset of patients with other cancer types that account for a substantial fraction of cancer related deaths worldwide." (PMID 39548594, 2024). "Moreover, knock-out of the target antigen Mesothelin on the same cancer cell lines was sufficient to escape CAR-mediated recognition and killing." (PMID 39781381, 2024). "Furthermore, mesothelin promotes cancer cell survival and proliferation through the activation of cyclin E and IL-6 signaling pathways." (PMID 38396817, 2024). "Moreover, cyclin E1 stimulation by mesothelin contributes to cancer cell proliferation and survival, which rely on ATP supply from both mitochondria and glycolysis." (PMID 38396817, 2024). "In cancer progression, MSLN is known to bind to the cancer antigen MUC16." (PMID 37546424, 2023). "Furthermore, it is crucial to assess the anticancer signaling cascades downstream of MSLN, a factor recognized for its role in fostering cancer cell survival and proliferation through the NFkB signaling pathway." (PMID 37894284, 2023). "Notably, both CD28 and 4-1BB mesoCAR T cells acquired MSLN antigen through trogocytosis from SKOV3 cells, leading to a subsequent loss of MSLN surface expression on the cancer cells." (PMID 37974170, 2023). "Patients with high MSLN expression levels on their cancers often have a poor prognosis." (PMID 36968141, 2023). "The complete structural information of MSLN could also guide the design and development of future MSLN-targeting cancer treatments." (PMID 36968141, 2023). "It is important to define the particular MSLN glycoforms in cancer, because a specific protein glycoform could improve the performance of the protein as a cancer biomarker." (PMID 36009489, 2022). "One such target that is under investigation is mesothelin, a cell-surface antigen that is normally found on mesothelial cells lining the pleura, peritoneum, and pericardium, and which is highly expressed in several types of cancer." (PMID 35565190, 2022). "Moreover, the typical expression pattern of MSLN in normal and cancer tissues makes it a promising target for therapeutic applications." (PMID 35565412, 2022). "Moreover, amatuximab was tested alone in another clinical trial (NCT01413451) on patients with cancers expressing high levels of mesothelin (including PDAC patients)." (PMID 35892707, 2022). "We first download the pan-cancer data of TCGA and GTEx and analyze the expression of MSLN." (PMID 35692779, 2022). "The MSLN gene is shown to be overexpressed in many cancers including ovarian cancer, adenocarcinoma, pancreatic cancer, mesothelioma, lung adenocarcinoma, acute myeloid leukemia, endometrial adenocarcinomas, and squamous cell carcinomas of the cervix, lung, head, and neck (Ordóñez, 2003)." (PMID 36387279, 2022). "AKT/PI3K/NF-κB pathways are activated by the overexpression of MSLN and subsequently induce resistance to apoptosis, which might help cancer cell survival in the highly inflammatory milieu." (PMID 36059490, 2022). "Mesothelin (MSLN) is another overexpressed molecule in several cancer cells." (PMID 36077739, 2022). "Some scholars believe that mesothelin may participate in cell adhesion and stimulate the growth of cancer cells." (PMID 35340746, 2022). "OPN and MSLN may serve as targets for immunotherapies and cancer vaccine development to treat ATRT patients." (PMID 35954348, 2022). "Conversely, MSLN is considered to be involved in several mechanisms of cancer pathogenesis." (PMID 35565412, 2022). "Cancer therapies targeting MSLN have been developed in recent years." (PMID 36434635, 2022). "Overexpression of MSLN indicates a poor prognosis for cancer patients." (PMID 35954348, 2022). "In cancer cells MSLN-Muc16 signaling increases cancer cell proliferation and metastasis." (PMID 34966784, 2021). "MSLN is overexpressed in cancer cells, including in lung cancer." (PMID 33025047, 2021).